HLA-DQB1 (major histocompatibility complex, class II, DQ beta 1)
Diseases named in the same sentence as HLA-DQB1 in open-access papers (continued):
Sharing a sentence is not in itself a finding about the gene and the disease.
IgG4-related pancreatitis (1 paper, 2023). "Another study by another Japanese group found six HLA class-associated variants, namely rs1143146 (HLA-A), rs1050716 (HLA-C), c.759_763delCCCCCinsTCCCG (HLA-C), rs1050451 (HLA-C), rs4154112 (HLA-DQB1), and rs1049069 (HLA-DQB1), to be associated with the relapse of IgG4-related pancreatitis." (PMID 36609529, 2023).
Lyme disease (1 paper, 2016). Lyme disease (named after the towns in the USA where the disease was first identified) is a bacterial infection caused by Borrelia burgdorferi. "Here we found that upregulation of certain HLA genes (HLA-DQA1, HLA-DQB1, HLA-DRB5) is associated with seronegativity in Lyme disease and may thus constitute potential diagnostic biomarkers for seronegative patients." (PMID 26873097, 2016). "While no DEGs were identified on the basis of single versus multiple lesions, four DEGs were found to be upregulated in seronegative Lyme disease patients relative to those who were seropositive, namely, HLA-DQA1, HLA-DQB1, HLA-DRB5, and NSA2." (PMID 26873097, 2016).
lymph node metastasis (1 paper, 2025). "We evaluated the correlations between HLA‐DQB1*05:02 genotypes and clinicopathological factors, such as tumor stage, age (< 40 vs. ≥ 40 years), lymph node metastasis, extra–nodal extension (ENE), and tumor differentiation." (PMID 40231636, 2025).
myeloma (1 paper, 2018). "LB-LILRB1-1I specific CD4 T-cells were incubated with myeloma cell-lines UM-6, UM-3, RPMI8226, and U266 transduced with HLA-DQB1*06:02." (PMID 30619360, 2018).
Myelopathy (1 paper, 2023). Myelopathy is an descriptive term, referring to pathology leading to a neurologic deficit related to the spinal cord. "In addition, a GWAS of HTLV-1-associated myelopathy/tropical spastic paraparesis (HAM/TSP) patients and asymptomatic HTLV-1 carriers identified HLA-DRB1*15:01 (reported P = 1.06 × 10−5, OR = 0.59) and HLA-DQB1*06:02 (reported P = 1.78 × 10−6, OR = 0.43) as top protective alleles." (PMID 37903429, 2023).
non-small cell lung carcinoma (1 paper, 2025). A group of at least three distinct histological types of lung cancer, including non-small cell squamous cell carcinoma, adenocarcinoma, and large cell carcinoma. "Specific HLA alleles, such as HLA-DRB1*11:01, have been linked to immune-related pruritus, and HLA-DQB1*03:01 has previously been shown to be associated with irColitis in metastatic melanoma and non-small cell lung cancer (NSCLC)." (PMID 40155873, 2025).
oropharyngeal cancer (1 paper, 2017). Carcinoma, predominantly squamous cell, arising from the epithelial cells of the oropharynx. "The HLA-DRB1*1301/HLA-DQA1*0103/HLA-DQB1*0603 haplotype has previously been associated with protection from oral and oropharyngeal cancer, particularly in HPV-positive cases (OR = 0.23, P = 1.6 × 10−6)." (PMID 28806749, 2017).
parasite infection (1 paper, 2021). "Thus, POR is indirectly responsible for regulation of expression of CIITA along with the molecules of MHC II group such as CD74, HLADQA1, HLADMA, HLADQB1 and HLADRB5 previously identified as genes responsible for inhibition of parasite infection." (PMID 34946170, 2021).
peanut allergies (1 paper, 2024). "The study showed that rs9275596 was a meQTL for the HLA-DRB1 and HLA-DQB1 genes, and that methylation was associated with risk of peanut allergies." (PMID 39355248, 2024).
psoriasis (1 paper, 2026). An autoimmune condition characterized by red, well-delineated plaques with silvery scales that are usually on the extensor surfaces and scalp. "Interestingly, some alleles, particularly HLA-DRB1*15:03g and HLA-DQB1*02:02g exhibited protective effects against psoriasis in the Brazilian population, further emphasizing the complex link between genetic factors and disease susceptibility." (PMID 41512531, 2026).
pulmonary edema (1 paper, 2019). Accumulation of fluid in the lung tissues causing disturbance of the gas exchange that may lead to respiratory failure. "Our finding was consistent with positive selection of HLA loci (HLA-DRA, HLA-DQB1/HLA-DQA2) in Ethiopian population and significantly associated with the high-altitude pulmonary edema of HLA-DR6 and HLA-DQ4." (PMID 31827636, 2019).
sleep disorder (1 paper, 2013). A change from the patient's baseline sleeping pattern, in the hours slept and/or an alteration/dysfunction in the stages of sleep. "Essential hypersomnia (EHS), a sleep disorder characterized by excessive daytime sleepiness, can be divided into two broad classes based on the presence or absence of the HLA-DQB1*06:02 allele." (PMID 23646285, 2013).
squamous cell carcinoma (1 paper, 2017). A carcinoma arising from squamous epithelial cells. "For squamous cell carcinoma, the strongest risk HLA allele associations were seen with HLA-DQB1*0602 (OR = 1.52, P = 1.47 × 10−7) and HLA-DRB1*1501 (OR = 1.50, P = 2.95 × 10−7)." (PMID 28806749, 2017). "As with squamous cell carcinoma, risk associations were seen between adenocarcinoma and HLA Class I (HLA-B*0702 (OR = 1.48, P = 2.65 × 10−5)) and Class II (HLA-DRB1*15 (OR = 1.49, P = 0.00012; HLA-DQB1*0602 (OR = 1.48, P = 0.00026) alleles." (PMID 28806749, 2017). "A reduced risk of squamous cell carcinoma was seen with both HLA Class I (HLA-B*15 (OR = 0.55, P = 4.78 × 10−6)) and HLA Class II alleles (HLA-DQA1*0103 (OR = 0.69, P = 0.006), HLA-DRB1*13 (OR = 0.71, P = 5.27 × 10−4), HLA-DQB1*0603 (OR = 0.69, P = 0.007))." (PMID 28806749, 2017). "In addition to the strong reduced risk of cervical neoplasia associated with HLA-B*15, the haplotype HLA-DRB1*1301/HLA-DQB1*0603 (and in some analyses HLA-DQA1*0103) was associated with reduced risk of squamous cell cancer, adenocarcinoma, and HPV16- and HPV18-related cervical neoplasia." (PMID 28806749, 2017).
Stroke (1 paper, 2019). Sudden impairment of blood flow to a part of the brain due to occlusion or rupture of an artery to the brain. "The expression of HLA-DRB1 and HLA-DQB1 was lesser in stroke patients than in normal controls (P < 0.05)." (PMID 31527307, 2019).
tauopathy (1 paper, 2016). Neurodegenerative disorders involving deposition of abnormal tau protein isoforms (tau proteins) in neurons and glial cells in the brain. "In contrast, when the information of the anti-IgLON5 antibodies status is missing but the clinical history is compatible or the patient harbored the HLA-DRB1*1001 and HLA-DQB1*0501 alleles, then the diagnostic category of “probable anti-IgLON5-related tauopathy” should be applied." (PMID 27358064, 2016).
thymoma (1 paper, 2025). A neoplasm arising from the epithelial cells of the thymus. "Among non-thymoma patients (n=14), the frequency of HLA-DQB1 03:03 (25% vs 15.9%, P = 0.195), HLA-C 01:02 (25% vs 15.9%, P = 0.195), HLA-B*52:01 (7.1% vs 3%, P = 0.669) was higher than that in the normal population, the difference was also not statistically significant." (PMID 41357573, 2025). "Among thymoma patients (n=9), the frequency of HLA-DQB1 03:03 (33.3% vs 15.9%, P = 0.057), HLA-C 01:02 (27.8% vs 15.9%, P = 0.167), HLA-B*52:01 (5.6% vs 3%, P = 1.0) was higher than that in the normal population, but the difference was not statistically significant." (PMID 41357573, 2025).
tuberculoid leprosy (1 paper, 2022). A principal or polar form of leprosy in which the skin lesions are few and are sharply demarcated. "Moreover, this transcript is consistently related to the tuberculoid leprosy (T-Lep) clinical form, while HLA-DQB1 has a strong relation with the L-Lep clinical form." (PMID 35492305, 2022).
tumor (44 papers, 2009 to 2025). "However, overexpression of HLA-DQB1 in RCC tissue revealed the complexity of the biological mechanisms underlying the process of tumor formation." (PMID 25784652, 2015). "NFATC2 and HLA-DQB1 played key roles in suppressing tumor growth by increasing T cell machinery through the activation of T cells and antigen presentation, respectively." (PMID 36545214, 2022). "PD-L1high tumours were significantly associated with HLA-DQB1high tumours (p < 0.001), and in total, 48% of the tumours (181/379) had collectively high PD-L1 and HLA-DQB1 levels." (PMID 33723390, 2021). "Of note, some tumours had scattered HLA-DQB1 staining patterns, with positive staining in Langerhans cells." (PMID 33723390, 2021). "Some key molecules, such as CALR, HLA-A, HLA-DRB1, PDIA3, HLA-DQB1, HLA-E, and TAP2, have been implicated in various types of cancers and emphasized their important values related to the tumor progression." (PMID 31258820, 2019). "In contrast, overexpression of HLA-DQB1 found in RCC tissue revealed the complexity of abnormal alterations in tumor tissue." (PMID 25784652, 2015). "Among them, HLA-DQB1 had the greatest difference between paired tumor and normal tissue with a 21% increased expression in RCC tumor tissues." (PMID 25784652, 2015). "For HLA-DQB1, both tumour and stromal protein level were considered (n = 389)." (PMID 33723390, 2021). "We found HLA-DQB1 to be the most upregulated gene within non-recurrent tumours and HLA-DQB1 protein levels associated significantly with favourable survival." (PMID 33723390, 2021). "More than 48% of the tumours had collectively high PD-L1 and HLA-DQB1 levels." (PMID 33723390, 2021). "We obtained results on the correlation between TPPP3 expression and marker genes of tumor infiltration-associated immune cells, including CD8+T cells (CD8A and CD8B), B cell (CD19 and CD79a), and Myeloid dendritic cell (HLA-DPB1, HLA-DQB1, HLA-DRA, HLA-DPA1, CD1C, NRP1, and ITGAX)." (PMID 33083464, 2020). "Our results could be important as increased HLA-DQB1 expression may enhance antigen presentation, immune surveillance and the elimination of tumor cells." (PMID 28139690, 2017). "The inflammation that occurs during cancer development may actually induce MHC expression in tissues or tumor cells, which may support the observation of higher expression level of HLA-DQB1 in RCC tissues." (PMID 25784652, 2015). "Furthermore, a number of interferon (IFN) response genes (BST2, CD74, HLA-DMA, HLA-DPB1, HLA-DQB1, HLA-DRA, HLA-DRB1, and IRF8) were upregulated in C10 compared to the other clusters, whereas genes associated with tumor suppression and apoptosis (TFF1 and TFF2) were downregulated." (PMID 37370788, 2023). "Conversely, the HLA-DQB1*02 allele is related to a lower treatment requirement, which could represent a protective allele in hiMBL/CLL, perhaps indicating that patients carrying this specificity are more able to control the CLL tumor clone." (PMID 28249016, 2017). "Moreover, the antigen-presenting genes HLA-DQA1 and HLA-DQB1 were strongly correlated with pseudotime in IBC tumour-infiltrating myeloid cells, suggesting that IBC tumour-infiltrating myeloid cells may promote humoral immunity by enhancing their antigen-presenting ability." (PMID 40624675, 2025). "TIMELESS expression was significantly negatively correlated with neutrophil biomarkers (CEACAM8) and dendritic cell biomarkers (HLA-DPB1, HLA-DQB1, HLA-DRA, HLA-DPA1, CD1C) in TCGA LUAD tumor tissues." (PMID 38261568, 2024). "Cluster Fib_5 prominently expressed MHC-II genes (HLA-DQA1, HLA-DQA2, HLA-DQB1, HLA-DRB5, HLA-DRB1, HLA-DRA, HLA-DPA1, and HLA-DPB1), indicating their role as antigen-presenting cells with tumor-suppressing effects." (PMID 37533434, 2023). "High LPAR6 expression relates to a high infiltration level of DCs in the tumor tissue of LUAD patients, DC markers such as HLA-DQB1, CD1C and NRP1 show significant correlations with LPAR6 expression both in the tumor tissue in LUAD." (PMID 34769557, 2021).
tumor (continued). "Several genes of antiviral immune response pathways such as HLA-B, HLA-C, HLA-DQB1 IFI6, IFITM3, CD74, and tumor suppressor genes EFEMP1 and EGR1, are upregulated in tumor and downregulated in TAS." (PMID 34316327, 2021). "Four genes (EPB41L2, HLA-DQB1, LTF and SFRP1) were consistently overexpressed across multiple PFS cutoff times in initial tumor samples of patients with disease progression following topotecan treatment." (PMID 31195594, 2019). "Four genes belong to the HLA family: HLA-DQA1, HLA-DRB1, HLA-DQB1, and HLA-F, which were significantly overexpressed in RCC tumor tissues compared with paired adjacent normal tissues." (PMID 25784652, 2015). "TIMELESS expression in LUAD tumor tissues was significantly negatively correlated with neutrophil biomarkers, dendritic cell biomarkers (HLA-DPB1, HLA-DQB1, HLA-DRA, HLA-DPA1, CD1C) and an immunophenoscore that predicted outcomes associated with the use of immune checkpoint inhibitors." (PMID 38261568, 2024). "Notably, genes such as NRG1, SAMD13, MFAP3L, SALL1, ZNF704, SEMA5A, and HLA-DQB1 were identified as having altered expression patterns, potentially reflecting the diverse roles of FGFRS in tumor biology." (PMID 39676867, 2024). "Notably, some genes related to exhaustion were also overexpressed in tumor‐infiltrating Tregs including TYMS, KIAA0101, CXCL13, CD27, HLA‐DQB1, HLA‐DMA, ENTPD1, CD200, DUSP4, and ZBED2." (PMID 32659053, 2020). "The results of VEGAS and the gene expression level comparison between RCC tumor and adjacent normal tissues indicated that major histocompatibility complex (MHC) loci, in particular HLA-DQB1, may contribute to RCC etiology." (PMID 25784652, 2015). "An interferon gene signature was also present in the profiles derived from the tumor epithelium of the ER-positive tumors (e.g., STAT1, IFIT1, IFIH1, IFI27, ISG15, OAS1, OAS3, OASL) and ER-negative tumors (e.g., HLA-DQA1 and HLA-DQB1)." (PMID 19225562, 2009). "However, cDCs in the PI3K/mTORi+PD‐1i‐treated tumours upregulated expression of genes related to antigen presentation via major histocompatibility complex class II (MHC II) (HLA‐DRB1, HLA‐DQB1, HLA‐DPB1, HLA‐DQB2, CD74) compared with cDCs in tumours treated with PD‐1i, PI3K/mTORi‐ or vehicle." (PMID 38711203, 2024). "It is worth noting that the interaction between HLA‐II molecules (such as HLA‐DRA, HLA‐DRB1, HLA‐DRB5, HLA‐DQB1, HLA‐DPB1, HLA‐DPA1, HLA‐DMB and HLA‐DMA) and the receptor CD4 was exclusively detected in the cell communication between malignant cells from single‐primary tumours and Tregs." (PMID 39601163, 2024). "However, analysis of single‐cell RNA‐sequencing (RNA‐seq) of GB patient tumors revealed that tumor cells do not express CIITA nor genes encoding for MHC‐II antigen processing (CD74, HLA‐DMA, HLA‐DOA) and presentation (HLA‐DQA1, HLA‐DQB1, HLA‐DRA, HLA‐DRB1, HLA‐DRB5)." (PMID 39535369, 2025). "When evaluating gene expression patterns in PD-L1high tumours by GSEA, only 24% of the significantly enriched GO gene sets (false discovery rate < 0.05) related to immune activation, indicating that HLA-DQB1 may be a stronger predictor for immune activation than PD-L1." (PMID 33723390, 2021). "Four genes (EPB41L2, HLA-DQB1, LTF and SFRP1) were consistently overexpressed in initial tumor samples of subsequent nonresponders across multiple PFS cutoff times." (PMID 31195594, 2019). "Notably, HLA-II expression in tumor cells was not uniform across the genes examined, with significantly higher HLA-DRB1 than HLA-DQA1, HLA-DQB1, and HLA-DPB1 (p < 0.0001, Kruskal–Wallis)." (PMID 35831288, 2022). "Other proteins, including HLA-A, HLA-DMA, HLA-DQA1, HLA-DQB1, HLA-DRA, HLA-DRB1, and HLA-DRB5, were not reported on tumor–host immunological interactions, which indicated the proteins need further studies to testify them as novel OC biomarkers for tumor immunology." (PMID 31258820, 2019).
cancer (25 papers, 2008 to 2024). A tumor composed of atypical neoplastic, often pleomorphic cells that invade other tissues. "A nominally significant association with cancer overall was observed for homozygosity at HLA-DQB1 locus (adjusted OR = 1.08, 95% CI = 1.01–1.15, P = 0.016)." (PMID 34421988, 2021). "This SNP affects the expression of the HLA-DQB1 gene, whose product may be associated with a protective effect against cancer." (PMID 37614503, 2023). "Nevertheless, there is biological plausibility for the association of HLA-DQB1 and cancer risk." (PMID 25784652, 2015). "Moreover, we found a variant in HLA-DQB1, replicated in an independent population, could alter cancer risk in a cis-eQTL manner." (PMID 25784652, 2015). "Although studies reported HLA-DQB1 being a promising prognostic marker in cancer patients, limited evidence was found regarding its predictive value of ICI therapy in GC patients, which warrants further validation." (PMID 38502852, 2024). "HLA class II molecules like HLA-DPB1, HLA-DRA, HLA-DRB1, and HLA-DQB1 are associated with antigen processing and presentation to CD4+ T cells, and the down-regulation of these genes is related to poor prognosis of cancers." (PMID 36417424, 2022). "As for MHC molecules, we found the MHC class II molecules including HLA-DPA1, HLA-DPB1, HLA-DRA, HLA-DRB1, HLA-DQA1, HLA-DQB1 showed a stronger relation with PD-1 than other MHC molecules in some cancer types." (PMID 30607140, 2018). "Although the HLA-DQB1 has been found to be associated with some cancers, however, the precise role of it has not yet been identified, a recent meta-analysis suggested that the variations occurred in HLA-DQB1 were related with the risk of HCC after pooling all available data." (PMID 27769059, 2016). "Several studies suggest that absence of HLA-DPA1 and HLA-DQB1 are correlated with poor prognosis of some cancers." (PMID 35486660, 2022). "Notably, HLA-A, HLA-DPA1, HLA-DQB1, HLA-DRA, HLA-DRB1, HLA-DRB5, and HLA-J consistently negatively correlated with the PLK1 expression in the 12 cancer types." (PMID 30631355, 2018). "Noteworthy were a number of hub genes like TLR4, FAS, HLA-DQB1, HLA-DQA1, F2, HLA-C, IFNAR1, which link complex diseases related to metabolic, immunological, infectious, cardiovascular, neuro-psychiatric disorders and cancer." (PMID 18782426, 2008).
infection (9 papers, 2011 to 2025). The state of being infected such as from the introduction of a foreign agent such as serum, vaccine, antigenic substance or organism. "HLA-DQB1*06 is also associated with a reduced risk of breakthrough infection based on PCR positivity after a median 494 days of follow-up after receiving their first dose of vaccine." (PMID 36228659, 2023). "Recent studies have highlighted the potential role of infection in the pathogenesis of IPF and a prior association of the HLA-DQB1 gene with idiopathic fibrotic interstitial pneumonia (including IPF) has been reported." (PMID 37546732, 2023). "DQB1*05:03:01G was only associated with Ct clearance and persistence events; however, previous studies have reported HLA-DQB1 (DQB1*06 and DQB1*04:02) alleles’ association with Ct infection and reinfection and increased bacterial persistence marker cHSP608,21,22." (PMID 34145318, 2021). "We found that HLA-DQB1*06 was present in 33.9% of individuals experiencing breakthrough infection compared to 45.6% of individuals who did not have breakthrough infection (chi-squared P = 0.02)." (PMID 36228659, 2023).
immune disease (5 papers, 2015 to 2025). "The analysis revealed the significant enrichment of genes such as HLA-DQB1, HLA-DPA1, S100A8, SFRP1, CD247, CTSH, and LAMP3, which are linked to inflammatory and immune disease pathways." (PMID 40426861, 2025). "HLA alleles play an important role in auto-immune diseases and the HLA families detected as eGenes from sun-exposed skin tissues were HLA-DQA1, HLA-DRB1, and HLA-DQB1." (PMID 31671645, 2019). "Among these, variants in HLA-C, HLA-DQB1 and HLA-DRB1 genes were found, a very significant finding in view of the important contribution of the HLA complex to immune disease susceptibility and pathogenesis." (PMID 31511551, 2019).